MIR214 (microRNA 214)
Synonyms: hsa-mir-214; MIRN214; miRNA214; mir-214
Gene: MicroRNA gene on chromosome 1 (172,138,798 to 172,138,907, reverse strand). Ensembl gene ENSG00000283844.
Gene Ontology:
Biological process: miRNA-mediated post-transcriptional gene silencing
Cellular component: RISC complex
Homologues: Orthologues: chimpanzee ptr-mir-214 (100% identical), guinea pig MIR214 (100% identical), macaque mml-mir-214 (100% identical), mouse Mir214 (100% identical), rabbit MIR214 (100% identical), rat Mir214 (100% identical), dog MIR214 (99% identical), pig ssc-mir-214 (99% identical), tropical clawed frog xtr-mir-214 (94% identical), zebrafish mir214a (73% identical). Paralogues in human: MIR3120 (55% identical).
Diseases named in the same sentence as MIR214 in open-access papers:
MIR214 is named in the same sentence as 2 diseases in open-access papers, as found by Europe PMC text mining. Sharing a sentence is not in itself a finding about the gene and the disease. The quoted sentences say what the papers report.
glioblastoma (1 paper, 2021). The most malignant astrocytic tumor (WHO grade IV). "We found previously uncharacterized miRNA genes in pediatric CNS tumors, including MIR149, MIR214, MIR574 and MIR765, apart from one study that reported MIR595 upregulation in glioblastoma compared to control cells, in vitro." (PMID 34204289, 2021).
CNS tumors (1 paper, 2021). "In cluster 2, MIR149, MIR214, MIR574, MIR595 and MIR765 were globally down-regulated across all CNS tumor samples; ten miRNA genes were also found globally down-regulated in >90% of all samples." (PMID 34204289, 2021).